VWF (von Willebrand factor)
Diseases named in the same sentence as VWF in open-access papers (continued):
Sharing a sentence is not in itself a finding about the gene and the disease.
thrombotic thrombocytopenic purpura (continued). "Thrombotic thrombocytopenic purpura (TTP) is a thrombotic microangiopathy caused by a severe functional deficiency in a disintegrin and metalloprotease with thrombospondin type I repeats-13 (ADAMTS13), the specific von Willebrand factor (VWF)-cleaving protease." (PMID 37176509, 2023). "Some studies have reported that increased ADAMTS13 levels are risk factors for various diseases such as diabetes, preeclampsia, liver cirrhosis, and thrombotic thrombocytopenic purpura because of the imbalance between ADAMTS13 and von Willebrand factor (VWF) levels in circulation." (PMID 34276770, 2021). "Considering the portrayed significance of the vWF-GPIb axis in preclinical ischemic-reperfusion injury models, caplacizumabs platelet-protective effect in thrombotic thrombocytopenic purpura (TTP) raises hope that this novel vWF-inhibitor might be protective in patients with ischemic stroke as well." (PMID 33123127, 2020). "In the absence of ADAMTS13, spontaneous formation of VWF-platelet complexes leads to thrombotic complications as seen in patients with thrombotic thrombocytopenic purpura." (PMID 31921147, 2019). "The absence of this protease prevents the breakdown of VWF and this contributes to life-threatening thrombosis in microvessels, a disorder called thrombotic thrombocytopenic purpura (TTP)." (PMID 25992814, 2015). "A more common TMA is thrombotic thrombocytopenic purpura, which is caused by the lack of normal ADAMTS-13-mediated cleavage of von Willebrand factor (VWF)." (PMID 23991205, 2013). "Acquired thrombotic thrombocytopenic purpura (TTP) occurs when anti-ADAMTS13 autoantibodies form and decrease serum levels of ADAMTS13, a protease that cleaves von Willebrand factor." (PMID 39963616, 2025). "Moreover, the recent use of nanobody technology to treat thrombotic thrombocytopenic purpura (TTP) may be of value, which binds to the A1 domain of the VWF, blocking its interaction with the platelet glycoprotein-Ib-IX-V receptor and therefore preventing platelet aggregation." (PMID 37987325, 2023). "The rare complication of thrombotic thrombocytopenic purpura with AP has also been reported clinically, and it is speculated that the systemic inflammatory reaction may affect the activity of VWF, but there is no experimental evidence to confirm this." (PMID 35745003, 2022). "Although thrombotic thrombocytopenic purpura (TTP) is related to the deficiency of metalloprotease ADAMTS 13 which is involved in the regulation of von Willebrand factor, both HUS and TTP share the same findings." (PMID 24637310, 2014). "Interestingly, in acquired thrombotic thrombocytopenic purpura (TTP), HNP-1 to -3 are reported to bind the central A2 domain of von Willebrand factor (VWF), thus blocking ADAMTS13 binding and providing a novel link between inflammation/infection and the onset of microvascular thrombosis." (PMID 40005828, 2025). "vWF’s contribution to pro-thrombotic conditions is dramatically demonstrated by thrombotic thrombocytopenic purpura (TTP), a condition in which the ultra-large vWF multimers released by endothelial cells are not reduced in size by the circulating metalloprotease ADAMTS13." (PMID 27576551, 2016). "With 5 Nbs currently in clinical trials, and the recent approval of caplacizumab (CabliviTM), a bivalent VHH targeting von Willebrand factor (vWF), by the EMA in October 2018 and the FDA in February 2019 for thrombotic thrombocytopenic purpura and thrombosis, this excitement is not surprising." (PMID 31544834, 2019).
Thrombocytopenia (150 papers, 2008 to 2026). A reduction in the number of circulating thrombocytes. "In patients with liver disease, an upregulation of VWF is associated with a re-compensation of hemostatic potential despite thrombocytopenia." (PMID 41091182, 2025). "The ensuing enzyme deficiency leads to the accumulation of ultra-large (UL) vWF multimers, which cause platelet aggregation and diffuse microvascular thrombosis, resulting in hemolytic anemia, thrombocytopenia, and organ ischemia." (PMID 40426866, 2025). "Decreased vWF levels seen with Caplacizumab, coupled with thrombocytopenia from TTP, predispose to the increased bleeding risk in these patients." (PMID 38406548, 2024). "Possibly, the thrombocytopenia is caused by the release of large amounts of vWF from endothelial activation which means a decrease of platelet counts can be suggestive of microthrombus formation." (PMID 36913975, 2023). "Prediction of thrombocytopenia and bleeding risk in patients with von Willebrand disease type 2B was studied by performing the quantification of the von Willebrand factor from plasma samples in its GPIb-α binding conformation using the AU/VWFa-11 nanobody." (PMID 37375810, 2023). "Hemostatic mechanisms that contribute to bleeding include thrombocytopenia, abnormal platelet function, clotting factor deficiencies, and depletion of von Willebrand factor." (PMID 35407516, 2022). "The most common cause is a factor-XI deficiency; other causes include the decreased activity of factors VIII and XII, vWF deficiency, thrombocytopenia and platelet functional defects." (PMID 35953836, 2022). "Abnormalities of GPIb-IX-V expression or an abnormal interaction between newly synthesized VWF with GPIb-IX-V in the megakaryocytes of a family with VWD2B caused by VWF R1308P lead to impaired megakaryocytopoiesis and thrombocytopenia." (PMID 34837956, 2021). "In platelet-type VWD, a gain of function mutation within platelet surface receptor for VWF leads to exaggerated platelet-VWF interaction, resulting in thrombocytopenia and consequently prolonged bleeding time." (PMID 34575297, 2021). "Desmopressin is not considered a therapeutic option because it causes the release of stored abnormal vWF, which can worsen thrombocytopenia." (PMID 32618441, 2020). "This reinforces the importance of VWF in platelet clearance and supports the possible use of VWF antagonists as adjunctive therapy for dengue-associated thrombocytopenia." (PMID 30849118, 2019). "Under basal conditions, the type of VWF mutation influences a patient’s thrombocytopenia, since individuals carrying the p.V1316M mutation had the most pronounced and persistent drop in their platelet count, and they also had giant platelets." (PMID 28640903, 2017). "Deficiencies of ADAMTS13 results in the accumulation of VWF in the circulation and, consequently, thrombocytopenia." (PMID 28296884, 2017). "An important function of VWF is to mediate platelet-platelet interactions and platelet adhesion to sub-endothelial collagen and is associated with platelet consumption and thrombocytopenia." (PMID 28296884, 2017). "In subtype 2B VWD, it is observed increased affinity of VWF by platelet glycoprotein Ib (GpIb) associated with loss of HMW-VWF and mild thrombocytopenia." (PMID 23970904, 2013). "Mutations in ADAMTS13 can be homozygous or compound heterozygous, which can result in either reduced production or increased clearance of the enzyme, leading to severe deficiency, an inability to cleave UL vWF multimers, platelet hyperaggregation, and consumptive thrombocytopenia." (PMID 40426866, 2025). "Thrombotic thrombocytopenia purpura (TTP), defined clinically by microangiopathic hemolytic anemia and thrombocytopenia, is attributed to either inherited or acquired loss of VWF multimer size regulation caused by severe ADAMTS13 deficiency, resulting in the accumulation of UL–VWF multimers." (PMID 38473925, 2024).
Thrombocytopenia (continued). "Concomitantly, the ECMO circuit can induce bleeding associated with thrombocytopenia, platelet dysfunction, shear-mediated loss of high molecular weight von Willebrand factor (VWF) multimers, hypofibrinogenemia, coagulation factor (F) consumption (including FXIII) and inflammation." (PMID 38337414, 2024). "Furthermore, the increased risk of bleeding in these patients is due not only to thrombocytopenia but also to reduced levels of large multimers of vWf." (PMID 36090551, 2022). "A gain-of-function mutation in the A1 domain causes spontaneous binding of vWF to GP1bα receptors on platelets, causing increased clearance of vWF multimers and platelets, and, additionally, abnormal vWF can modify megakaryocytopoiesis, both of which result in thrombocytopenia." (PMID 32618441, 2020). "The antibiotic ristocetin induces binding of VWF to platelets and may cause thrombocytopenia, and as a consequence, it was removed from clinical practice." (PMID 30849118, 2019). "In line with this, enhanced endogenous binding of mutant vWF to GPIbα in patients with vWF disease-type 2B results in giant platelets and thrombocytopenia and was reported to be associated with dysregulation of the LIM kinase/cofilin pathway in MKs, together with upregulated RhoA signalling." (PMID 28643773, 2017). "What happens after type 2B VWF has interacted with platelets seems to depend on their platelet count because the disappearance of large VWF multimers is associated with transient or persistent thrombocytopenia." (PMID 28640903, 2017). "VWF excess is therefore associated with platelet consumption and thrombocytopenia." (PMID 28296884, 2017). "However it appears unlikely that such a mechanism accounts for a marked thrombocytopenia, such as observed with the VWF/p.V1316M mutation." (PMID 26645283, 2015). "Additionally, plasma vWF levels (including ultra-large vWF multimers) are increased in patients with malaria, also associated with increased GPIb shedding from platelets and the development of thrombocytopenia." (PMID 31572400, 2019). "This is similar to the mechanism by which caplacizumab, the only TTP-specific therapeutic agent, binds to the A1 domain of vWF, thus stopping the chain of events that leads to platelet binding and subsequent thrombocytopenia." (PMID 40136473, 2025). "This shift occurs through the inhibition of protein C activation and the binding of PF4 to von Willebrand factor, resulting in thrombocytopenia and substantial thrombin generation." (PMID 40276517, 2025). "PLT function was often preserved in cirrhotic patients with thrombocytopenia and compensatory elevation of VWF has been observed in cirrhotic thrombocytopenia." (PMID 41341826, 2025). "Thrombocytopenia seems to balance the increase in platelet aggregation that results from the increase in vWF and the decrease in ADAMTS13 activity." (PMID 39458229, 2024). "Maintenance of EC integrity, improved thrombocytopenia, decreased vWF levels, and vWF-mediated platelet-EC interactions are responsible for these anti-sepsis effects." (PMID 38921594, 2024). "Thrombocytopenia is attributed to splenic sequestration and decreased thrombopoietin; however, this situation is offset by an increase in vWF." (PMID 37189710, 2023). "In patients with severe neurotoxicity, thrombocytopenia was observed alongside highly elevated von Willebrand Factor (vWF), which is usually stored as ultra-large vWF multimers in Weibel-Palade bodies of endothelial cells and released upon activation." (PMID 37864230, 2023). "It is most commonly caused by a deficiency of factor XI followed by a reduced activity of factors VIII, XII, von Willebrand factor (vWF), thrombocytopenia, and platelet functional defect." (PMID 37910477, 2023). "Platelets from VWF-/- mice infused with sheared VWF expressed CD62p, developed moderate thrombocytopenia and generated more VWF+ pEVs." (PMID 35411318, 2022).
Thrombocytopenia (continued). "CTL-like protein generates platelet aggregation by indirectly modulating the von Willebrand factor (vWF) and promoting thrombocytopenia." (PMID 36287984, 2022). "In terms of predictive laboratory markers, baseline thrombocytopenia, and baseline elevated markers of endothelial activation, such as angiopoietin-2 (ANG2) and von Willebrand factor (vWF), have been associated with the development of severe CRS." (PMID 36172391, 2022). "First, patients with type 2D VWF disease usually suffer from thrombocytopenia and accelerated clearance of different severity since their VWF is mutated and has a constitutive affinity to GPIb." (PMID 35366951, 2022). "In vEA-VMTD promoted by activated complement system following vaccination, “consumptive” thrombocytopenia develops as ITP-like syndrome due to activated unusually large von Willebrand factor (ULVWF) path of hemostasis via microthrombogenesis." (PMID 34833382, 2021). "Caplacizumab is a humanized, bivalent von Willebrand factor (vWF)-specific nanobody dimer, which inhibits the interaction between vWF multimers and platelets, thereby preventing thrombocytopenia, hemolytic anemia, and tissue ischemia." (PMID 34131806, 2021). "Histones induce the release of von Willebrand factor (VWF) from Weibel-Palade bodies (WPBs) in endothelial cells and cause platelet activation and thrombocytopenia." (PMID 33999963, 2021). "H&E staining and VWF immunohistochemistry results revealed that DMAG elevated the number of BM megakaryocytes in mice with thrombocytopenia." (PMID 34837956, 2021). "Another example of thrombocytopaenia due to desialylation induced by excessive binding of VWF to platelets is that observed in patients infected by the dengue virus." (PMID 33924503, 2021). "Thrombocytopenia can also result from endothelial sequestration, wherein platelets increasingly attach to von-Willebrand factor (vWF) on vascular endothelial cells, resulting in small clogs in microcirculation and low levels of platelets in peripheral blood." (PMID 32074143, 2020). "Endothelial activation occurs in HELLP and increased active von Willebrand factor (vWF) levels can contribute to thrombocytopenia in the HELLP syndrome." (PMID 32351511, 2020). "This thrombocytopenia is compensated, however, by elevated levels of adhesive protein vWF and decreased ADAMTS-13." (PMID 33425821, 2020). "Overall, thrombocytopenia in ALF is compensated by elevated levels of vWF, reduced ADAMTS-13 levels and presence of platelet-derived extracellular vesicles that partially offset the impact of low platelet count." (PMID 33425821, 2020). "This deficiency of ADAMTS13 was associated with both high vWF:Ag and ULVWF concentrations as well as with thrombocytopenia and increased LDH concentrations." (PMID 32122366, 2020). "Similar to humans, clinical conditions characterized by a decline in blood platelets (thrombocytopenia) or vWF levels (von Willebrand factor disease) can lead to dysfunctional hemostasis and thrombosis in mice." (PMID 32765527, 2020). "It thereby supports the notion that VWF is important in the etiology of dengue-induced thrombocytopenia, as binding of VWF to platelets is expected to result in platelet clearance." (PMID 30849118, 2019). "Thrombocytopenia is often (at least partly) compensated by an increase of von Willebrand factor (VWF) levels." (PMID 29875796, 2018). "Having seen thrombocytopenia in acute melioidosis, we predicted that this would be driven by high levels of circulating VWF." (PMID 28296884, 2017). "Uncleaved von Willebrand factor (VWF) multimers accumulate and bind to platelets which causes spontaneous microthrombi ultimately causing microangiopathic hemolytic anemia, thrombocytopenia, and end-organ ischemia." (PMID 28367342, 2017).
Thrombocytopenia (continued). "The resulting loss of large VWF multimers in patients with type 2B VWD is associated with moderate or severe, persistent or transient thrombocytopenia, sometimes associated with the presence of giant platelets and circulating platelet aggregates." (PMID 28640903, 2017). "Rapid chemokine and cytokine production, as well as Ad5-induced thrombocytopenia mediated by p-selectin and von Willebrand factor (vWF), are all elicited in a C3-dependent manner, with the help of other complement factors such as C2 and C1q." (PMID 26610547, 2015). "TTP is a life-threatening disorder that is characterized by systemic platelet-VWF aggregation, organ ischemia, profound thrombocytopenia and fragmentation of erythrocytes." (PMID 26022055, 2015). "Thrombocytopenia due to abnormal platelet aggregation is usually recognized in patients with high VWF/ADAMTS13 ratio." (PMID 25960882, 2014). "In patients with cirrhosis and thrombocytopenia, maintenance of normal primary hemostasis seems to depend greatly on concomitantly increased vWF levels and reduced levels of the vWF cleaving protease ADAMTS13." (PMID 25397410, 2014). "Acquired TTP is associated with decreased metalloprotease ADAMTS-13 activity, which is a protease responsible for cleaving von Willebrand factor (vWF) multimers; failure to degrade vWF results in platelet aggregation and subsequent thrombocytopenia." (PMID 24649385, 2014). "The thrombocytopenia in hepatosplenic schistosomiasis is compensated, at least in part, by increased levels of von Willebrand factor that enable platelets to adhere and aggregate at sites of vascular injury." (PMID 23875049, 2013). "In vivo, a single injection of rTM protected mice against histone-induced thrombocytopenia, VWF-rich intravascular thrombus formation, dilatation of the right ventricle, pulmonary hemorrhage, and death." (PMID 24098750, 2013). "Elevated levels of VWF seen in patients with cirrhosis are due to thrombocytopenia and decreased VWF protein, cleaving protease ADAMTS13." (PMID 22164337, 2011). "Recombinant human IL-11 (rhIL-11, Neumega), a glycoprotein 130- (gp130-) signaling cytokine that is approved for treatment of thrombocytopenia, has been shown to induce elevations in VWF and F.VIII in humans and mice." (PMID 22091368, 2010). "This suggests that T-TAS reflects the interaction of platelets with VWF and that the effect of thrombocytopenia in the HD-chip may be overcome by the high VWF-activity in our group of patients with myeloid malignancies." (PMID 41091182, 2025). "This may suggest that endothelial activation drives vWF release, facilitating platelet adhesion to the vascular wall and contributing to platelet depletion in severe malaria, where thrombocytopenia and microvascular obstruction are common complications." (PMID 40283058, 2025). "Decreased ADAMTS13 activity leads to a buildup of the ultra large vWF multimers along endothelial walls, resulting in platelet-rich microthrombi and the characteristic triad of thrombocytopenia, hemolytic anemia, and end-organ ischemia characterizing the disease." (PMID 40136473, 2025). "In type 2B VWD, release of gain-of-function (hyperadhesive) VWF may lead to aggravation of thrombocytopenia." (PMID 37601016, 2023). "According to the helpful algorithm proposed by Favaloro, prolonged COL/EPI CTs with normal COL/ADP CTs could be attributed to drug effect, low Hct, mild thrombocytopenia, and mild platelet/von Willebrand factor (VWF) dysfunction." (PMID 36160789, 2022). "Also, the aminoglycoside ristocetin as well as the snake venom botrocetin increase the interaction between GPIb and VWF and can induce thrombocytopenia." (PMID 35366951, 2022). "A second venom CTL, aspercetin, has been shown to induce thrombocytopenia via vWF, though the specific vWF domain(s) and platelet-binding site it targets is unknown." (PMID 35723968, 2022).